APP (amyloid beta precursor protein)
Diseases named in the same sentence as APP in open-access papers (continued):
Sharing a sentence is not in itself a finding about the gene and the disease.
Alzheimer disease (continued). "The overproduction of the toxic peptide amyloid-beta (Aβ) generated from the cleavage of amyloid precursor protein (APP) is proposed to be a critical event in the development of Alzheimer's disease." (PMID 38799759, 2024). "APP was first discovered in the context of Alzheimer’s disease, and its function has been gradually elucidated over the years." (PMID 39351084, 2024). "In an Alzheimer’s disease model of APP/PS1 mice, decreased levels of brain parenchymal lactate and various MCT subtypes were observed." (PMID 38671979, 2024). "A defective NLRP3 inflammasome was found to result in reduced Aβ deposition in the APP/PS1 model of Alzheimer’s disease." (PMID 37940779, 2024). "We began our study with three critical proteins involved in Alzheimer’s Disease—tau, APP, and BACE1." (PMID 38540368, 2024). "Inefficient RQC during APP synthesis generates CAT-tailed species that precipitate hallmarks of Alzheimer’s disease." (PMID 38311171, 2024). "EA was administered to APP/PS1 Alzheimer's disease (AD) mice, with untreated AD, and wild type (WT) mice serving as controls." (PMID 39320044, 2024). "For example, genome editing of the APP gene’s 3’-UTR in a humanized knock-in mouse model led to reduced Aβ pathology, highlighting the efficacy of CRISPR/Cas9 in mitigating Alzheimer’s Disease through protective mutations." (PMID 39691161, 2024). "This is an important finding for understanding the physiological function of APP, a key protein for Alzheimer’s disease." (PMID 38745463, 2024). "Chronic nobiletin treatment enhances the amplitude or expression of clock genes in the peripheral tissues and cortex of young and older high-fat-diet-treated or Alzheimer’s disease model (APP/PS1) mice." (PMID 38794729, 2024). "It is well established that impaired sorting of APP in the endo-lysosomal system leads to an elevated production of the amyloid β-peptide, which is one of the cardinal pathologies of Alzheimer's disease (AD)." (PMID 38368933, 2024). "During Alzheimer’s disease (AD), Amyloid β (Aβ) is produced from the amyloid precursor protein (APP)." (PMID 39456151, 2024). "In Alzheimer’s disease, a major culprit is the amyloid-beta (Aβ) peptide, a fragment derived from the amyloid precursor protein (APP)." (PMID 39684324, 2024). "Consistent with prior results in other models of Alzheimer’s disease, we found that in dCA1, SWRs occurred less frequently in APP/PS1 mice than in C57BL/6 controls." (PMID 38709845, 2024). "In APP/PS1 Alzheimer`s disease (AD) model mice, GCN2 deletion alleviates defects in synaptic plasticity and memory." (PMID 39319345, 2024). "They include Alzheimer’s disease (AD) (APP and presenilin genes), familial British and Danish dementias (BRI gene), and cases of Gerstmann-Sträussler-Scheinker disease (prion protein gene)." (PMID 38758288, 2024). "Small animal PET was performed using [18F]GSK1482160 in widely used mouse models of Alzheimer's disease (APP/PS1, 5×FAD, and 3×Tg), 4-repeat tauopathy (rTg4510) mice, and age-matched wild-type mice." (PMID 38776461, 2024). "For this purpose, a PubMed search was performed using “APP gene and Alzheimer’s disease and brain memory” as the keywords; the results included many studies on APP and their impact on memory function." (PMID 38396891, 2024). "In summary, there are numerous target pathways that intersect with both myelin repair and Alzheimer's disease pathophysiology, including APP processing, ApoE signaling, and tau-Fyn processing." (PMID 39285941, 2024). "The 3,4-dihydroxybenzoic acid reduced Aβ levels in the hippocampus and cerebral cortex of amyloid precursor protein (APP)/presenilin-1 (PS1) transgenic Alzheimer’s disease (AD) model mice." (PMID 39519743, 2024). "APP is a widely expressed transmembrane protein that is thought to play a function in the development of Alzheimer’s disease." (PMID 38388341, 2024). "The Aplp2 codes for the amyloid-beta precursor protein that produces amyloid-β toxin in humans with Alzheimer’s disease." (PMID 38334607, 2024).
Alzheimer disease (continued). "To investigate the potential of silencing NOX4 in mitigating iron-induced cell death and alleviating Alzheimer’s disease, we conducted experiments on APP/PS1 transgenic mice by employing NOX4 knockdown and erastin treatment." (PMID 38956702, 2024). "APP plays a crucial role in the pathogenesis of Alzheimer’s disease, as it serves as the precursor to the amyloid-beta protein that forms amyloid plaques, a pathological hallmark of the disease." (PMID 38474215, 2024). "In the study of Alzheimer’s disease, it was discovered that although APP itself is a target of miRNA regulation, amyloid β protein can downregulate miRNAs, including miR-181c and miR-9, both of which inhibit the expression of TGFBI." (PMID 38725646, 2024). "APP has been extensively studied as a precursor of amyloid β neurotoxic peptides in Alzheimer’s disease." (PMID 39109301, 2024). "It has been shown that the APP proteolytic product β-amyloid (Aβ) accumulates in skeletal muscle in Alzheimer's disease." (PMID 38311171, 2024). "In the cerebrovascular systems of tissues affected by atherosclerosis and Alzheimer’s disease (AD), the protein levels of APP, phosphorylated APP (Tyr682), and β-amyloid (Aβ) are elevated." (PMID 39726810, 2024). "Genetic models, such as mice with mutations in amyloid precursor protein (APP), presenilin-1 (PS1), or PDGF-B genes, replicate Alzheimer’s disease pathology and pericyte deficiency, leading to sustained BBB disruption." (PMID 39337280, 2024). "In the current study, animals were dosed at 625 mg/kg in chow, a dosage that was calculated from ACY-738 chow administration in APP/PS1 mice modelling Alzheimer's disease, which led to ∼100 mg/kg ACY-738 ingested." (PMID 39130445, 2024). "The amyloid precursor protein (APP) is a key protein in Alzheimer’s disease synthesized in the endoplasmic reticulum (ER) and translocated to the plasma membrane where it undergoes proteolytic cleavages by several proteases." (PMID 38992438, 2024). "Amyloid precursor protein (APP), the biological precursor of β-amyloids, has been extensively studied in relation to Alzheimer’s disease, where it is involved in angiogenesis." (PMID 38962272, 2024). "Simultaneously, both Aβ and the δ‐secretase‐truncated APP C586‐695 (C110) fragments stimulate the transcription of Alzheimer's disease‐related genes by binding to and activating C/EBPβ, which encompasses δ‐secretase." (PMID 38644578, 2024). "An Alzheimer’s disease mouse model (5xFAD) deficient of MT5-MMP showed reduced Aβ formation and maintained learning by promoting enhanced trafficking of APP to the endo-lysosomal compartment." (PMID 38992438, 2024). "BACE1, an enzyme that cleaves Amyloid Precursor Protein (APP) and produces Amyloid β (Aβ), is a promising target for Alzheimer's Disease (AD) treatment." (PMID 38965280, 2024). "More specifically, we detect alterations of lactate diffusion in the APP/PS1 mouse model of Alzheimer’s disease." (PMID 38950371, 2024). "Initially, gamma-secretase inhibitors were developed for Alzheimer's disease research, targeting the production of beta-amyloid peptides from amyloid precursor protein (APP)." (PMID 38844562, 2024). "APP is a well-known protein often discussed in the context of Alzheimer’s disease, but it is also responsible for many functions in the body under normal and pathological conditions, including TBI." (PMID 39595962, 2024). "We next investigated the role of reactive astrogliosis in the APPSwe/PSen1dE9 (APP/PS1) model of Alzheimer’s disease (AD)." (PMID 38289036, 2024). "Although lower Tc is a biomarker of successful aging, we have previously shown this worsens cognitive performance in the APP/PS1 mouse model of Alzheimer’s disease (AD)." (PMID 39614130, 2024). "Synaptic dysfunction and abnormal processing of amyloid precursor protein (APP) are early pathological features of Alzheimer's disease (AD)." (PMID 38125754, 2024).
Alzheimer disease (continued). "The Rab1A isoform is a key regulator of early endosome sorting and this protein is also thought to be involved in the transport and processing of the APP protein in Alzheimer’s disease." (PMID 38645276, 2024). "The production of neurotoxic amyloid-β peptides (Aβ) is central to the initiation and progression of Alzheimer's disease (AD) and involves sequential cleavage of the amyloid precursor protein (APP) by β- and γ-secretases." (PMID 39302110, 2024). "The transmembrane protein β-amyloid precursor protein (APP) is central to the pathophysiology of Alzheimer’s disease (AD)." (PMID 39125997, 2024). "Molecular and genetic studies in AD patients have identified three primary genetic mutations associated with Early-Onset Alzheimer’s Disease (EOAD), linked with genes encoding amyloid precursor protein (APP), presenilin 1 (PSEN1), and presenilin 2 (PSEN2)." (PMID 39000011, 2024). "To address this question, we first examined the expression of FAM92A1 in aged mice (10 months old) and the APP/PS1 transgenic mouse model for early-onset Alzheimer’s disease (AD)." (PMID 39043703, 2024). "Autosomal dominant Alzheimer's disease (ADAD) is a rare form of Alzheimer's disease (AD) that arises from mutations in the genes encoding presenilin 1 (PSEN1), presenilin 2 (PSEN2), or amyloid precursor protein (APP), all affecting APP processing." (PMID 38666355, 2024). "Neurotoxic β-amyloid peptides (Aβ) are major drivers of Alzheimer’s disease (AD) and are formed by sequential cleavage of the amyloid precursor protein (APP) by β-secretase (BACE1/2) and γ-secretase, respectively." (PMID 39439934, 2024). "One of the central events to Alzheimer’s disease (AD) pathology is the aberrant processing of amyloid precursor protein (APP), resulting in the generation of various Aβ peptides." (PMID 39404364, 2024). "Alzheimer’s disease (AD) is a progressive neurodegenerative disorder characterized by dysregulation of the expression and processing of the amyloid precursor protein (APP)." (PMID 38311171, 2024). "The Arctic mutation, encoding E693G in the amyloid precursor protein (APP) gene [E22G in amyloid-β (Aβ)], causes dominantly inherited Alzheimer’s disease." (PMID 36611124, 2023). "The amyloid precursor protein (APP) is located on chromosome 21 and is linked to gout as a genetic risk factor for Alzheimer’s disease, which can induce disease through interaction with the mutated HPRT1." (PMID 38060535, 2023). "For example, aldehyde dehydrogenase 2 family member (ALDH2) ameliorated cardiac systolic dysfunction in an amyloid precursor protein (APP)/presenilin 1 (PS1) murine model of Alzheimer’s disease by inhibiting ACSL4-dependent ferroptosis." (PMID 37372148, 2023). "Our results demonstrate a conserved role for APP in controlling age-dependent proteostasis with plausible relevance to Alzheimer’s disease." (PMID 37923712, 2023). "To illustrate the interplay between HSV-1 and the host neuronal cells potentially involved in chronical pathology such as Alzheimer’s disease, we have analyzed the modifications of the wild type APP metabolism induced by infection." (PMID 36898995, 2023). "Alzheimer’s disease (AD) is characterized by specific hallmarks, including the accumulation of Amyloid Beta (Abeta) oligomers, which are derived from Amyloid Precursor Protein (APP) processing." (PMID 37174636, 2023). "In overall, these results suggest that Ngfr signaling reduces amyloid and Tau pathology concomitant to enhancing adult hippocampal neurogenesis in APP/PS1dE9 mouse model of Alzheimer’s disease." (PMID 37429840, 2023). "The amyloid precursor protein (APP) plays an essential role in Alzheimer’s disease (AD), since sequential cleavages of β- and γ-secretase lead to the formation of the 4 kDa Aβ peptide, which accumulates in brains of AD patients." (PMID 37533067, 2023).
Alzheimer disease (continued). "In mouse models of Alzheimer's disease (AD) with overexpression of either amyloid precursor protein (APP) or presenilin, inconsistent changes in neurogenesis have been observed." (PMID 38025664, 2023). "The effects of multifocal cerebral microinfarcts on the development of Alzheimer’s disease (AD) in male and female APP/PS1 mice were investigated in this work." (PMID 37508939, 2023). "Two of the main neuronal changes identified histopathologically in Alzheimer’s disease are the presence of the amyloid precursor protein (APP) and neurofibrillary tangles." (PMID 37889645, 2023). "To study juvenile Alzheimer’s disease in a patient with Down’s syndrome, excess copies of APP from T21 strain we removed using CRISPR-Cas9 and APP gene expression was boosted using inducible CRISPRa." (PMID 38031028, 2023). "Despite the dominant focus on Aβ peptides in Alzheimer’s disease research, a number of functions for APP have nonetheless been defined using biochemical, cellular and genetic approaches." (PMID 37923712, 2023). "Beta secretase 1 (BACE1, A01.004) is a membrane-anchored pepsin-like aspartic protease, which prefers hydrophobic recognition stretches and cleaves the amyloid precursor protein (APP) as a critical step in the development of Alzheimer’s disease." (PMID 37762340, 2023). "Mutations in the presenilin-1 (PSEN1), presenilin-2 (PSEN2), and amyloid precursor protein (APP) genes have been commonly identified in early-onset Alzheimer's disease (EOAD)." (PMID 37051054, 2023). "Alzheimer's disease is characterized by abnormal cleavage of Amyloid Precursor Protein (APP) by beta-secretase, which results in the extracellular accumulation of insoluble amyloid beta plaques." (PMID 37273267, 2023). "In an APP/PS1 mutant mouse model of Alzheimer’s disease (AD), the neuronal nuclear morphology varies with plaque size and with increasing distance from the plaque." (PMID 36819109, 2023). "In Alzheimer’s disease (AD), in particular, the amyloidogenic processing of the amyloid precursor protein (APP) intimately revolves in and around the endolysosomal system." (PMID 37225734, 2023). "CDN1163 has been demonstrated to be effective in the APP/PS1 double transgenic mouse model of Alzheimer’s disease." (PMID 37762276, 2023). "In APP/PS1 transgenic mice that exhibit early Alzheimer’s disease, an increase in Ins was observed in the frontal cortex and hippocampus with aging, but there is no study examining the level of mIns in the vestibular cortex." (PMID 36835808, 2023). "The decrease in the number of pyramidal cells and thickness of CA1 and CA3 regions have also been reported in Alzheimer’s-like disease induced by scopolamine and in APP/PS1 transgenic mouse models of Alzheimer's disease." (PMID 37231523, 2023). "Amyloid peptide (Aβ), generated by proteolytic cleavage of amyloid precursor protein (APP), plays an important role in the pathogenesis of Alzheimer’s disease (AD)." (PMID 37626806, 2023). "Using previously published data, we show that genes in the RhoA/ROCK signaling cascade are highly upregulated in the neurodegenerative microglia (MGnD) from APP/PS-1 transgenic Alzheimer’s disease (AD) mice." (PMID 37408199, 2023). "Autophagy in Alzheimer’s disease has been shown to target membrane-bound amyloid precursor protein (APP, the precursor of β-amyloid) for degradation, providing substantial support for autophagy-mediated degradation of membrane proteins via adaptor proteins." (PMID 38077388, 2023). "Blockade of the IL-1 receptor with anakinra resulted in a significant increase in cognitive capacity in healthy mice as well as in the APP/PS1 model of Alzheimer ́s disease." (PMID 37187754, 2023). "Alzheimer ́s disease (AD) is the most prevalent form of dementia and involves the amyloid precursor protein (APP) playing a key role in the pathology of AD." (PMID 37259128, 2023).
Alzheimer disease (continued). "Specifically, our research group has reported that a reduction in IGF-I levels in aging or APP/PS1 animal models of Alzheimer's disease induced an improvement in the neuronal activity in different brain areas." (PMID 37475984, 2023). "The secretory pathway has long been implicated in Alzheimer’s disease pathogenesis with the first findings coming from studies of EOAD, where the Swedish mutation results in differences in Amyloid precursor protein (APP) sorting." (PMID 38168398, 2023). "γ-Secretase is an attractive drug target for Alzheimer’s disease because it is responsible for the final cleavage in the processing of the amyloid precursor protein (APP) to Aβ peptides." (PMID 38072061, 2023). "In a mouse model of Alzheimer’s disease, miR-21 and miR-181c effectively reduced amyloid-β accumulation and increased synaptic protein expression and miR-21 levels in the brains of APP/PS1 mice." (PMID 36875046, 2023). "The emerging world faces a genetic risk of Alzheimer’s disease (AD) due to mutations in PSEN1 (located on chromosome 14), PSEN2 (located on chromosome 1), and APP (located on chromosome 21), which are known to cause familial Alzheimer’s disease (FAD)." (PMID 38173557, 2023). "Despite decades of research on Alzheimer’s disease and APP, we are still far from a complete understanding of its biological basis." (PMID 37834241, 2023). "Most of the effects on cell signaling have been detected in the Alzheimer’s disease context and/or in the APP-transgenic mouse models in which the concentrations of Aβ peptides exceed the physiological ones." (PMID 37305553, 2023). "In our study, a blood-brain barrier crossing flavonol glycoside hyperoside was identified with anti-Aβ aggregation, BACE inhibitory, and neuroprotective effect in cellular or APP/PSEN1 double transgenic Alzheimer's disease mice model." (PMID 36821955, 2023). "It was determined by us in our latest paper that ovoC induced changes in the expression of Alzheimer’s disease—Aβ and tau proteins in APP/PS1 mice model." (PMID 36982505, 2023). "In turn, the increased TGFB2 binds to the extracellular domain of amyloid beta precursor protein and triggers a neuronal cell death pathway in Alzheimer’s disease." (PMID 37107654, 2023). "Neuroretina and retinal vasculature are affected by altered amyloid precursor protein (APP) processing and fibrillar Aβ deposition in transgenic Alzheimer’s disease animal models." (PMID 36674027, 2023). "γ-Secretase is an aspartyl intramembrane protease that cleaves the amyloid precursor protein (APP) involved in Alzheimer’s disease pathology and other transmembrane proteins." (PMID 37355752, 2023). "Regarding Presenilin-2, it is part of the complex that catalyzes the cleavage of APP and mutations in PSEN2 are causative of dominantly inherited Alzheimer’s disease." (PMID 37784196, 2023). "Overall, studies of APP imply that APP palmitoylation, APP dimerization, and aging contribute to the development of Alzheimer’s disease." (PMID 36766729, 2023). "Firstly, amyloid precursor protein (APP) is of great interest to the researchers focusing on Alzheimer’s disease." (PMID 37511374, 2023). "For example, the central protein in Alzheimer’s disease, the amyloid precursor-protein (APP), contains cholesterol-binding motifs in its transmembrane sequence." (PMID 37533630, 2023). "A plethora of studies unraveled the dysregulation of Amyloid Protein Precursor (APP) as one of the most validated hallmarks of Alzheimer’s disease." (PMID 36898995, 2023). "It has been shown to directly regulate the amyloid-β precursor protein (APP) and Ran-binding protein 9 (RanBP9) as well as MAPK1, which are all implicated in the pathology of Alzheimer’s disease." (PMID 37584866, 2023). "The amyloid precursor protein (APP) is a key molecular component of Alzheimer’s disease (AD) pathogenesis." (PMID 37830617, 2023).